EGFR (epidermal growth factor receptor)
Diseases named in the same sentence as EGFR in open-access papers (continued):
Sharing a sentence is not in itself a finding about the gene and the disease.
rectal tumors (12 papers, 2007 to 2025). "Patients with rectal tumors were predominantly male and potential candidates for anti-EGFR therapy (47.4%)." (PMID 38409377, 2024). "Left-sided colon or rectal tumors more frequently have chromosomal alterations, amplification of EGFR and HER2 genes, and aberrant EGFR signaling." (PMID 38473410, 2024). "Generally, the majority of rectal tumor cases occurred in males, who were often suitable for anti-EGFR therapy, with 47.4% qualifying for this treatment." (PMID 38409377, 2024). "Another retrospective analysis of two Phase II Spanish trials described a reduced unconfirmed ORR (64% vs 80%, CI = 0.2–0.9) but similar PFS and OS in the rectal tumour group treated with anti-EGFR, which is different from our results to some degree." (PMID 34188197, 2021). "Among them, 39% of right-sided colon, 43% of left-sided colon and 47% of middle/low rectal tumours were treated with first-line anti-EGFR therapy." (PMID 34188197, 2021). "Immunohistochemistry (IHC) for EGFR was performed on 82 rectal tumour biopsies and 1197 MMR-proficient CRCs using a tissue microarray." (PMID 17311026, 2007). "EGFR was considered to be overexpressed when more than 15% of cells were stained when evaluating rectal tumour response to HDREB but was significantly greater when analysing features related to tumour progression and survival (⩾75% staining)." (PMID 17311026, 2007). "Mucinous rectal tumors are more likely to be MSI-H, BRAF mutated and KRAS mutated which could potentially result in an impaired response to cytotoxic chemotherapy and EGFR inhibitors although this is only a hypothesis and needs to be confirmed prospectively with a much larger cohort." (PMID 32984045, 2020). "Similarly, in left-sided colon and rectal tumors, ORR was 100% in patients treated with doublet chemotherapy, anti-EGFR therapy, and triplet therapy, while it was 85% in the anti-VEGF group." (PMID 40428735, 2025). "Re-biopsy of the rectal tumor was obtained to assess for mechanisms of resistance and sequencing identified FGFR1 and EGFR gene amplifications; and an E1A binding protein p300 (EP300) mutation in codon L1755V, and a Wolf-Hirschhorn Syndrome Candidate 1-Like 1 (WHSC1L1) mutation in codon E123Q." (PMID 28915719, 2017). "Analysis revealed a mutation in KIT at codon G961S, PIK3CA and MYC gene amplifications that were not noted on prior testing and confirmed FGFR1 and EGFR amplifications which were previously identified in the progressed rectal tumor tissue." (PMID 28915719, 2017). "In particular, EGFR expression was significantly higher in the right-sided tumors than the left-sided and rectal tumors, independent of MMR status; in contrast, TOPO1 expression was higher in rectal tumors compared to the right-sided and left-sided colon, again independent of MMR status." (PMID 29156800, 2017). "Epigenetic modifications that confer sensitivity to EGFR-targeted therapy (e.g., demethylation of the EREG promoter) occur more commonly in rectal tumors, but such epigenetic modifications were not assessed in our study." (PMID 29156800, 2017).
sarcomatoid carcinoma (12 papers, 2005 to 2025). A malignant epithelial neoplasm characterized by the presence of spindle cells and anaplastic morphologic features. "Another episode of histological transformation into sarcomatoid carcinoma occurred 11 months later and the EGFR mutation assay showed 19Del as well as loss of T790M mutation." (PMID 35888627, 2022). "Eight sarcomatoid carcinoma were analyzed for the presence of EGFR kinase domain mutations, KRAS mutations, HER2 kinase domain mutations, BRAF mutations, ALK fusions, RET fusions and AKT1 mutations." (PMID 26486077, 2015). "PSC exhibits high KRAS and EGFR mutation rates, and spindle cell carcinoma has a worse prognosis." (PMID 39720986, 2025). "The histological transformation from NSCLC to sarcomatoid carcinoma occurs in 2.5–4.8% of patients after failure of treatment with first/second and third-generation EGFR-TKIs." (PMID 41226501, 2025). "Furthermore, patients with a transformation from adenocarcinoma to sarcomatoid carcinoma after EGFR-TKI treatment experience epithelial-to-mesenchymal transitions." (PMID 35888627, 2022). "Besides, one case had sarcomatoid carcinoma transformation and two cases had squamous transformation from adenocarcinoma in EGFR 19delins cohort." (PMID 34774017, 2021). "More recently, a study showed that the expression of epidermal growth factor receptor (EGFR) was positive in the majority of sarcomatoid carcinomas of the upper urinary tract, suggesting that anti-EGFR molecular targeted therapy may be a promising therapeutic direction in the future." (PMID 25120689, 2014). "Taken together, these findings suggest that EGFR overexpression and/or gene amplification are likely to play a role in carcinomas with squamous elements and spindle cell carcinomas, but perhaps not in the other subtypes of MBC." (PMID 16280056, 2005).
sarcopenia (12 papers, 2020 to 2025). Progressive decline in muscle mass due to aging which results in decreased functional capacity of muscles. "We aimed to evaluate the impact of sarcopenia on erlotinib therapy and prognosis in patients with EGFR-mutated (exon 19 or 21 L858R) metastatic lung adenocarcinoma." (PMID 35575465, 2022). "Sarcopenia was highly prevalent in NSCLC patients harboring EGFR mutations and treated with gefitinib." (PMID 36471329, 2022). "Our study aimed to evaluate the impact of sarcopenia on erlotinib therapy and prognosis in patients with metastatic lung adenocarcinoma harboring EGFR mutations." (PMID 35575465, 2022). "Consequently, we sought to investigate the potential predictive value of sarcopenia on the efficacy of EGFR-TKIs in NSCLC patients harboring EGFR mutations or of ICIs in patients with wild-type EGFR." (PMID 36969820, 2023). "In addition, although the data are contradictory, sarcopenia in NSCLC patients treated with EGFR-TKIs has been identified as a risk factor of poor prognosis and shorter survival." (PMID 36145591, 2022). "The present study presents considerable real-world data on sarcopenia as a prognostic marker in patients with advanced NSCLC receiving first-line EGFR-TKIs or ICIs." (PMID 36969820, 2023). "Among all patients, 35 (26.7%) were diagnosed with sarcopenia, including 17 EGFR-TKI-treated and 18 ICI-treated patients." (PMID 36969820, 2023). "The only study that examined the association of both measures (sarcopenia and BMI) with outcomes in patients with NSCLC and EGFR mutation was a retrospective study of 167 patients who received gefitinib, erlotinib, or afatinib as a first or later line therapy." (PMID 33194687, 2020). "Sarcopenia should be considered before using EGFR-TKIs or ICIs in clinical practice." (PMID 36969820, 2023). "The underlying mechanisms by which sarcopenia affects the efficacy of ICIs and EGFR-TKIs are not yet fully understood." (PMID 36969820, 2023). "Therefore, in this study, we aimed to assess the association between sarcopenia and clinical outcomes in patients with advanced NSCLC receiving EGFR-TKIs or ICIs as a first-line therapy." (PMID 36969820, 2023). "In conclusion, sarcopenia before first-line EGFR-TKI or ICI therapy might be a significant predictor of poor clinical outcomes, leading to shortened OS and PFS and reduced OR and DC." (PMID 36969820, 2023). "The mechanism by which sarcopenia affects the efficacy of EGFR-TKIs is still unclear, but some of the reasons may be similar to those for immunotherapy drugs, such as drug clearance." (PMID 36969820, 2023). "In the few studies evaluating the prognostic impact and predictive value of sarcopenia in NSCLC patients harboring EGFR mutations and treated with EGFR-TKIs, as with ICI therapies, the results are inconsistent; however, most studies agree that sarcopenia does not affect PFS and OS." (PMID 36969820, 2023). "A retrospective study showed that sarcopenia did not affect the response to gefitinib in patients with EGFR-mutated NSCLC." (PMID 36969820, 2023). "Therefore, nutritional intervention and physical activity programs are recommended to patients with sarcopenia receiving immunotherapy or EGFR-TKI therapy to improve the therapy outcome." (PMID 36969820, 2023). "In a retrospective study that evaluated gefitinib outcomes in patients with EGFR-mutated NSCLC according to their sarcopenia status, they found that sarcopenia did not affect PFS and treatment-related toxicity." (PMID 35575465, 2022). "Therefore, as the diffusion and disposition of drugs in fat are different from those in muscle, this could be one of the mechanisms by which sarcopenia affects the prognosis and toxicity of EGFR-TKIs." (PMID 36969820, 2023).
sarcopenia (continued). "However, the impact of sarcopenia on the efficacy and toxicity of EGFR-TKIs and ICIs remains unclear." (PMID 36969820, 2023). "In EGFR-TKI therapy nutritional status and body composition, including BMI and sarcopenia, have been identified as important prognostic factors." (PMID 41425618, 2025). "Another study has shown that sarcopenia present before starting treatment predicts worse OS and PFS in patients receiving EGFR-TKIs." (PMID 41425618, 2025). "Sarcopenia was an independent predictor of poor OS and PFS (p < 0.05) overall and in the EGFR-TKI- and ICI-treated cohorts." (PMID 36969820, 2023). "Then, MC-sarcopenia targets were filtered to obtain four core proteins, namely PIK3CA, AKT1, EGFR, and INS." (PMID 35176999, 2022). "Seven main active components (Anonaine, Eucalyptol, Neohesperidin, Obovatol, Honokiol, Magnolol, and beta-Eudesmol) and 26 target proteins of MC-sarcopenia, of which 4 were core proteins (AKT1, EGFR, INS, and PIK3CA), were identified." (PMID 35176999, 2022). "We confirmed that patients with sarcopenia had significantly shorter OS and PFS than those without sarcopenia in the entire patient, EGFR-TKI-treated, and ICI-treated cohorts." (PMID 36969820, 2023). "The general benefits of nutrition supplements after cancer diagnosis include the cooperative effects with anticancer RT, the activation of tumor apoptosis, the downregulation of EGFR and VEGF pathways in cancer cells, and the attenuation of cancer-induced sarcopenia." (PMID 32872195, 2020). "In brief, there is no consensus as to whether sarcopenia is a prognostic biomarker for EGFR-TKI or ICI treatment of advanced NSCLC, especially when used as the first-line treatment." (PMID 36969820, 2023). "Sarcopenia before treatment might be a significant predictor of poor clinical outcomes (shorter OS and PFS, fewer ORs, less DC) in patients with advanced NSCLC treated with EGFR-TKIs or ICIs as the first-line therapy." (PMID 36969820, 2023). "Furthermore, the results of molecular docking showed that there exists direct hydrogen bondings between the active components (Honokiol, Magnolol, and Obovatol) of MC and the core proteins of sarcopenia (AKT1, EGFR, INS, and PIK3CA), which verifies our analysis and prediction from another angle." (PMID 35176999, 2022). "In the EGFR-TKI-treated cohort (n = 77), the median OS and PFS for patients with sarcopenia were significantly shorter than those for patients without sarcopenia (OS: 12.7 vs. 28.0 months; PFS: 8.6 vs. 14.1 months, respectively; both p < 0.001)." (PMID 36969820, 2023). "Similarly, using univariate and multivariate analyses of EGFR-TKI subgroups, we found that patients without sarcopenia had significantly longer OS and PFS than those with sarcopenia." (PMID 36969820, 2023).
toxicity (12 papers, 2014 to 2025). The degree to which an agent can damage an organism. "In NSCLC patients harboring identified EGFR mutations, the incidence of gefitinib-induced hepatic injury was even greater, with 50–70% of patients developing drug-induced liver toxicity and 16–26% of these with grade 3–4 injury." (PMID 24527096, 2014). "Skin toxicity (ST) is the most prevalent side effect associated with EGFR inhibitors." (PMID 40664764, 2025). "Skin toxicity is the most common adverse reaction observed with epidermal growth factor receptor (EGFR) inhibitors and checkpoint inhibitors such as anti-CTLA4 agents (T-lymphocyte-associated antigen 4) and anti-PD-1 agents (programmed cell death protein-1)." (PMID 30069667, 2018). "Consistent with prior evidence that skin toxicity is a class effect of EGFR mAbs, 41 patients (93.2%) experienced some form of skin or subcutaneous disorder regardless of grade or relationship to study therapy." (PMID 26766738, 2016). "Although skin toxicity during anti-EGFR treatment might be considered a minor, non–life-threatening side effect, it is known to markedly impact patients’ QoL." (PMID 38422495, 2024). "Although EGFR inhibitors have good efficacy for a variety of tumors, adverse reactions such as skin toxicity, interstitial lung disease, hepatotoxicity, ocular toxicity, hypomagnesemia, stomatitis, and diarrhea may occur during treatment." (PMID 35223483, 2022). "We assumed very severe skin toxicity would interrupt the treatment temporarily and EGFR inhibitors may be continued among these patients based on NCCN guidelines." (PMID 30459532, 2018).
uveal melanoma (12 papers, 2004 to 2026). A melanoma derived from melanocytes of the uveal tract. "HIF-1α, Akt, ERK, and EGFR protein levels all decreased in uveal melanoma cell lines after combination treatment." (PMID 35804893, 2022). "EGFR overexpression was associated with worse OS cutaneous and nasal melanoma, but not uveal melanoma." (PMID 36212475, 2022). "Moreover, uveal melanoma cell lines representing high expression of MET/EGFR possessed higher migration potential." (PMID 31638339, 2019). "Of the 4 samples that had an IndexSUM of <300 and the 6 samples that demonstrated >50% inhibition at 100% TDC when tested with single agent gefitinib, 2 samples (a uveal melanoma and an unknown primary) had material available for immunohistochemical staining with EGFR and pAkt." (PMID 15560844, 2004). "A recent study suggested that combining the HDI entinostat with dual human epidermal growth factor 2 and the epidermal growth factor receptor neratininb leads to internalization and degradation of mutant GNA11 and GNAQ in uveal melanoma models." (PMID 34533562, 2021). "Compensatory pathways are known to be activated in uveal melanoma, including HGF-c-Met, SRC, Ras, EGFR, VEGF, and phosphatidylinositol-3-kinase-AKT signaling." (PMID 32976223, 2020). "Knockdown of MET, as well as selective inhibitors of EGFR, decreased proliferation of high MET‐expressing uveal melanoma cells." (PMID 31638339, 2019). "The uveal melanoma was negative for EGFR and positive for pAkt compared to the unknown primary, which was positive for both EGFR and pAkt." (PMID 15560844, 2004). "Consistent with the role of Hsp90 in promoting HIF-1α and Akt stability, 80 μM and 160 μM cordycepin treatment significantly decreased protein levels of HIF-1α, Akt, ERK, and EGFR in ADA-low (92.1, MM28, Omm1) uveal melanoma cell lines, but not in those with high ADA (MP46 and MP38)." (PMID 35804893, 2022).
acinar adenocarcinoma (11 papers, 1996 to 2025). "At diagnosis, there were 83 (72.8%) stage I/II patients, 76 (66.7%) with acinar adenocarcinoma, and a total of 48 (42.1%) cases and 14 (12.3%) patients with EGFR mutations and other mutations, including KRAS and ALK, respectively." (PMID 32154654, 2020). "By histological subtype, 8 of 11 cases (72.7%) of papillary adenocarcinoma, 3 of 4 cases (75%) of BAC; bronchiolo-alveolar carcnoma expressed in, and one of 7 cases (14.3%) of acinar adenocarcinoma expressed EGFR mutation." (PMID 27070423, 2016). "However, most of the infiltrating foci were fibrotic stroma with only a few acinar adenocarcinoma cells, and the EGFR mutation possibility was low (heatmap in blue)." (PMID 37407963, 2023). "EGFR‐mutated tumors showed lower GLUT1 protein expression (P = 0.017), corresponding with the fact that predominantly lepidic and acinar adenocarcinomas are EGFR mutated and demonstrate low GLUT1 expression." (PMID 31668020, 2019). "EGFR mutations were found in predominantly lepidic and acinar adenocarcinomas and not in adenocarcinomas with a predominantly papillary or solid growth pattern (not significant)." (PMID 31668020, 2019). "High expression PD-L1 is a poor factor on PFS and OS in patients with WT, clinical stage III/IV or acinar adenocarcinoma, but has no significant impact on patients with early stage and EGFR mutations." (PMID 30972298, 2019).
acute respiratory distress syndrome (11 papers, 2021 to 2025). Progressive and life-threatening pulmonary distress in the absence of an underlying pulmonary condition, usually following major trauma or surgery. "CASP3 controls apoptosis to preserve tissue integrity, ALB maintains plasma oncotic pressure to prevent pulmonary edema and reduce the risk of acute respiratory distress syndrome, and EGFR promotes tissue repair." (PMID 40723395, 2025). "EGFR is capable of engaging in numerous cellular responses, serving as an integral component of the cytokine storm, and is implicated in the onset of severe acute respiratory distress syndrome." (PMID 39654679, 2024). "On the other side, EGFR overactivation has been associated with acute respiratory distress syndrome (ARDS) and fibrosis development." (PMID 34354180, 2021). "Acute respiratory distress syndrome (displayed an acute pulmonary edema) has been reported in individual patients receiving EGFR-CAR-T therapy." (PMID 34553036, 2021). "IL-1β has also been reported to promote the development of acute respiratory distress syndrome (ARDS) by regulating CLDN18 through the human epidermal growth factor receptor (HER) pathway (IL-1β-HER2/HER3 axis)." (PMID 38806818, 2024).
carcinoma in situ (11 papers, 2007 to 2025). "Furthermore, we also found that the frequency of carcinoma in situ among the nodules with other type gene mutation (n = 8, 14.1%) or wildtype gene (n = 28, 25.7%) was higher than those with EGFR mutation (n = 5, 5.1%) (P < 0.001)." (PMID 37124493, 2023). "A locoregional pilot study to evaluate the feasibility, tolerability, and efficacy of 213Bi-anti-EGFR mAb treatment in patients with bacillus Calmette-Guerin (BCG) refractory carcinoma in situ (CIS) was performed." (PMID 33919391, 2021). "Moreover, the pathological features of increased malignancy, such as tumor invasion, were associated with HER2, demonstrated by significant EGFR and HER2 mRNA expression in invasive matrix-producing carcinoma compared to in situ carcinoma." (PMID 36356060, 2022).